CRP (C-reactive protein)
Diseases named in the same sentence as CRP in open-access papers (continued):
Sharing a sentence is not in itself a finding about the gene and the disease.
viral infections (continued). "It is possible that patients with an identified viral infection and elevated procalcitonin or CRP might also be harbouring an undetected pathogenic bacterial infection, as documented for example in hypotensive dengue patients with translocation of gut bacteria." (PMID 26558692, 2015). "The results highlighted CRP's role in balancing metabolic and immune homeostasis during viral infection." (PMID 41878438, 2026). "Point-of-care C-reactive protein (CRP) testing can support the distinction between bacterial and viral infections, but its diagnostic accuracy is often compromised by chronic inflammatory comorbidities that elevate baseline CRP levels." (PMID 42192732, 2026). "This would also fit the pattern that viral infections, which usually lead to type I IFN production, are associated with lower CRP levels than bacterial infections." (PMID 40632603, 2025). "Elevated CRP levels are found in many conditions, from bacterial or viral infections to chronic inflammatory diseases and cardiovascular diseases." (PMID 40141715, 2025). "Similar findings have been noted in other studies, where CRP was found to have limited utility as a marker of disease progression in viral infections like bronchiolitis." (PMID 40426750, 2025). "Laboratory parameters that significantly influenced outcomes in both viral infections included elevated C-reactive protein, LDH, and NLR, as well as a high ACCI score." (PMID 40871340, 2025). "With MxA predominantly elevated in viral infections and CRP levels higher in bacterial infections, the ratio of MxA to CRP has been proven to improve the accuracy of differentiating these infections." (PMID 39861921, 2025). "Since both psoriasis and viral infection involve significant immune activation and chronic inflammation, there is a need to investigate the prevalence of viral infections in psoriasis patients with elevated resistin and CRP levels." (PMID 40724556, 2025). "In children >7 months of age, lower mean SpO2 levels have been observed in cases of bacterial-viral infections, along with a threefold increase in CRP, indicating a more severe infection." (PMID 41210881, 2025). "The levels of procalcitonin and CRP in the bloodstream assist medical professionals in distinguishing between bacterial and viral infections, thus leading to correct antibiotic therapy choices." (PMID 40871295, 2025). "Children with unexplained fever and low CRP had differentially expressed genes linked to interferon-induced immune responses, including IFIT1, IFIT2, and IFIT3, commonly upregulated during viral infections." (PMID 40806258, 2025). "A prominent example is the FDA-cleared FebriDx® assay, which distinguishes between bacterial and viral infections by concurrently detecting C-reactive protein (CRP) and myxovirus resistance protein A (MxA)." (PMID 40942842, 2025). "Elevated CRP levels are routinely used to differentiate bacteria from viral infections, to support the diagnosis of community-acquired pneumonia, and to guide antibiotic stewardship." (PMID 41010302, 2025). "More recently, myxovirus resistance protein A (MxA) has gained attention as a promising viral infection marker, especially when used in combination with CRP, offering improved specificity in distinguishing bacterial from viral etiologies." (PMID 40142420, 2025). "By assessing the degree of SAA and combining it with CRP, it is possible to differentiate between bacterial and viral infections more accurately." (PMID 40920832, 2025). "We also observe that in both the S. aureus and E. coli bloodstream infection groups, CRP and neutrophil counts are significantly higher than in the viral infection and healthy control groups." (PMID 40903799, 2025). "It has a faster onset than CRP and is specific for bacterial infections, with lower levels in viral infections." (PMID 40003700, 2025). "Using a cutoff of 5.15 mg/L, CRP exhibited low specificity (33%) in discriminating viral infections, with an AUC value of 0.44." (PMID 41065831, 2025).
viral infections (continued). "CRP is typically elevated in bacterial infections, but its levels can also rise in severe viral infections, thereby providing insights into the host’s inflammatory status." (PMID 40868809, 2025). "The reasons also contribute to the inability of MxA/CRP to effectively distinguish between the viral infection group and the viral-bacterial co-infection group." (PMID 40046054, 2025). "C-reactive protein can help to differentiate between bacterial and viral infections as well as to determine the bacterial infection’s severity." (PMID 41463723, 2025). "Although liver dysfunction is commonly observed in viral infections, the increase in CRP levels typically remains mild following RSV infection alone." (PMID 39941446, 2025). "CRP and PCT are commonly elevated in bacterial infections and are widely used as diagnostic biomarkers to distinguish bacterial from viral infections." (PMID 39861921, 2025). "These markers were markedly lower in the viral infection group compared to the bacterial infection group, with CRP showing the most significant difference." (PMID 40046054, 2025). "Since CRP directly contributes to antibacterial, but not antiviral, defence, IFNα-dependent suppression of IL6-dependent CRP induction has resource-saving effects in the context of viral infections." (PMID 40632603, 2025). "It is also worth noting that CRP levels can fluctuate due to various illnesses, including asymptomatic viral infections." (PMID 41367212, 2025). "In this study, MxA and the combined use of MxA/CRP can effectively differentiate viral infections from bacterial infections, but they fail to show significant differences between viral infections and mixed infections." (PMID 40046054, 2025). "Theoretically, CRP is expected to perform well in distinguishing between viral infections and viral-bacterial co-infections." (PMID 40046054, 2025). "The CRP levels can be used to differentiate bacterial from viral infections since CRP is more elevated in the case of bacterial infections." (PMID 39766578, 2024). "One study classified pulmonary exacerbation events according to viral infection status and systemic C-reactive protein (CRP) levels, and found that biomarker profiles, clinical presentation and outcomes differed between pulmonary exacerbation classes." (PMID 38135443, 2024). "Elevated CRP levels indicate an excessive inflammatory response following viral infection and often suggest a poor prognosis." (PMID 38835792, 2024). "There is a study that indicates a host-protein score (BV score), which combines the expression levels of TNF-related apoptosis-induced ligand, interferon gamma-induced protein 10, and C-reactive protein, helping to differentiate bacterial from viral infection." (PMID 39770373, 2024). "Our findings highlight IL-6 as the most promising candidate biomarker for diagnosing viral diseases, with AUC higher than 0.85, surpassing arachidonic acid and CRP." (PMID 39066228, 2024). "In clinical practice, healthcare providers typically use a combination of tests, including CRP levels, white blood cell counts, and specific pathogen tests, to help differentiate between bacterial and viral infections." (PMID 39201697, 2024). "Second, a gold standard for assessing the performance of the host-protein signature score was created by establishing strict inclusion criteria (CRP levels of > 5 mg/dL and fever, PCR-positive viral infection, or positive blood culture)." (PMID 39249176, 2024). "With viral infection, IL-6 production increases, along with macrophage activation syndrome, increasing CRP." (PMID 38785752, 2024). "Viral infection can cause an innate immune response, including elevated erythrocyte sedimentation rate (ESR), C-reactive protein (CRP), serum amyloid A, and ferritin levels, and an increase in some inflammatory cytokines." (PMID 38510081, 2024).
viral infections (continued). "The overlapping coefficient for OPG was 0.31 while for CRP was 0.17 indicating that the overlapping values for serum OPG between the bacterial and viral infection groups was much higher, compared to CRP." (PMID 38509997, 2024). "A 2022 study analyzed the effectiveness of using the estimated C-reactive protein velocity (eCRPv) as a novel marker to differentiate between acute bacterial and viral infections." (PMID 39201697, 2024). "HNL has better clinical performance in differentiating between bacterial and viral infections compared to CRP, CD64, and PCT." (PMID 39559703, 2024). "We explored the correlations between anti-HAV and anti-HBV antibodies, CRP levels as a marker of inflammation, and thyroid hormone levels to gain insight into the broader physiological effects of viral infections." (PMID 39205303, 2024). "Borrelia-positive patients were distinct from viral infections in elevated CRP (Mann–Whitney two-sided, p = 0.030), IL-10 (p = 0.00038), and MIP-1Beta (p = 0.0048) and decreased IP-10 (p = 0.00028), IFN-alpha (p = 0.0022), and MCP-1 (p = 0.00038)." (PMID 38272885, 2024). "Alongside the OPG data, the serum CRP levels, as expected, were significantly increased in bacterial compared to the viral infection group (p < 0.001)." (PMID 38509997, 2024). "CRP, a widely used biochemical marker of inflammation, reflects acute and severe systemic inflammatory responses resulting from viral infection." (PMID 38957300, 2024). "In fact, moderately elevated CRP values can also be found in severe or untreated viral infections, such as viral infections of the upper respiratory tract or lower respiratory tract." (PMID 39064460, 2024). "Clinical laboratory results show that SARS-CoV-2-positive and co-infected children under 5 years of age usually show mild elevations in CRP levels (mean: 16.2 mg/L), which is common in viral infections." (PMID 39457522, 2024). "The increase of CRP has been reported in several viral infections, such as H1N116 and recent SARS-CoV217–19." (PMID 38698064, 2024). "Commonly used biomarkers like C-reactive protein (CRP) and erythrocyte sedimentation rate (ESR) also face challenges due to their susceptibility to various elements, including bacterial and viral infections, compromising their sensitivity and specificity." (PMID 38533316, 2024). "Studies have demonstrated that electrochemical biosensors were effectively monitor CRP levels, providing a sensitive and rapid method for assessing inflammation during viral infection." (PMID 39589620, 2024). "Minding the decreased reliability, CRP levels seemed lower in viral infections compared to bacterial infections." (PMID 39237955, 2024). "Blood exams are usually evocative of viral infection, with C-reactive protein (CRP) and white blood cells (WBC) normal or just slightly elevated." (PMID 38251362, 2024). "In this study, calprotectin, procalcitonin, and CRP demonstrated a similar performance in the detection of bacterial infections and in distinguishing between bacterial and viral infections in infants aged 1–3 months." (PMID 38786153, 2024). "Among these proteins, CRP, SAA1, and SAA2 are described as common markers for inflammation and combined monitoring of CRP and serum amyloid A has previously been shown to increase specificity for monitoring viral infections." (PMID 39441646, 2024). "These include urine dipsticks to diagnose urinary tract infections, rapid throat swabs to identify Group A Streptococcal infections, and C-reactive protein (CRP) POCTs performed on blood from a finger prick to differentiate bacterial from viral infections." (PMID 38504318, 2024). "The study found that eCRPv values were significantly higher in patients with bacterial infections compared to those with viral infections, particularly in cases with intermediate CRP levels, where the diagnosis is often uncertain." (PMID 39201697, 2024).
viral infections (continued). "Elevated CRP concentrations have been observed in bacterial infections, severe viral infections (such as H1N1 influenza pneumonia), and, currently, in SARS-CoV-2 infection." (PMID 38304653, 2024). "It is considered that CRP values above 80–100 mg/L are associated with bacterial superinfections, but these figures are rarely reached in children with bronchiolitis, and many viral infections moderately elevate CRP overall." (PMID 38133281, 2023). "Especially, the combination of MxA and CRP, markers for viral infections and inflammation, respectively, offers promising results as a rapid point of care test in children and adults with respiratory infections." (PMID 36737561, 2023). "Generally, it has been found that patients with a viral infection have low neutrophil count, low to normal concentration of C-reactive protein (CRP), and elevated concentration of myxoma resistance protein (MxA1) compared to patients with bacterial pneumonia." (PMID 38130539, 2023). "Several biomarkers such as C-reactive protein (CRP), procalcitonin and IL-6 have been introduced into clinical decision making to discriminate between cases caused by bacterial or viral infection." (PMID 37371198, 2023). "The manifestation of CRP levels in ongoing infectious processes, although is diagnostically important to differentiate between bacterial and viral infections, its role in determining the course of infection is also being extensively researched." (PMID 39554800, 2023). "The involvement of CRP in determining the course of infection and differentiating between bacterial and viral infections has also been investigated." (PMID 39554800, 2023). "The blood panel revealed elevated levels of ESR and CRP indicative of inflammation via viral infection; however, the results also showed abnormal levels of TSH and T4 hormones consistent with thyroiditis, suggesting hyperthyroidism." (PMID 37489189, 2023). "The observation that all four VAEs that we detected in the SISCAPA cohort are associated with elevations of both CRP and SAA suggests that time-dense measurements of these inflammatory markers can provide a sensitive measure of viral infection." (PMID 36997517, 2023). "We correlated CRP levels to a particular focus of bacterial or viral infection and Plasmodium parasitemia." (PMID 37478118, 2023). "Compared with the CRP level, the PCT level is considered a more useful diagnostic biomarker for differentiate between bacterial and viral infections." (PMID 37144031, 2023). "Studies have shown that GDF15 is related to inflammatory cytokines, such as IL-6 and CRP, suggesting an essential role in maintaining inflammation throughout viral infections." (PMID 37408184, 2023). "An increase in WBC indicates a promotion in the cellular immune system response to control viral infection and as a result, an increase in the inflammatory cytokines expression such as IL-10 and CRP." (PMID 37396915, 2023). "PCT or CRP has a high AUC value for distinguishing bacterial and viral infections, consistent with previous reports, but the inadequate sample size contributed to the exceptionally high AUC values." (PMID 37822360, 2023). "A host-protein score (BV score) that combines the circulating levels of TNF-related apoptosis-inducing ligand (TRAIL), interferon gamma-induced protein 10 (IP-10) and C-reactive protein (CRP) was developed for distinguishing bacterial from viral infection." (PMID 36716321, 2023). "CRP means were comparable in bacterial infection and malaria, and in both of these conditions, levels were significantly higher than in viral infections (p<0.0001)." (PMID 37478118, 2023). "Elevated CRP is considered as an essential indicator of infection, including bacterial and viral infection and chronic inflammation." (PMID 37168805, 2023). "As expected, a high level of CRP in the blood was produced early after viral infection, and a considerable reduction in CRP levels by LDRT was observed on all days." (PMID 37304302, 2023).
viral infections (continued). "The combination of CRP and MxA in a single test has the potential of reliably differentiating bacterial from viral infections." (PMID 38202172, 2023). "The arithmetic means (with min and max values shown in parentheses) of CRP in malaria, bacterial infection and viral infection were 80.79mg/L (6.0–315.7), 84.41mg/L (0.23–324.0) and 17.82mg/L (0.2–237.36), respectively." (PMID 37478118, 2023). "PCT, CRP and eosinophils (EO) were also able to distinguish bacterial infections from viral infections, with AUC values of 1, 1 and 0.929, respectively." (PMID 37822360, 2023). "Acute-phase reactant serum amyloid A (A-SAA) is used in clinical laboratories as an indicator of inflammation and is more conclusive than the detection of CRP in patients with viral infections, and severe acute pancreatitis." (PMID 37953798, 2023). "C-reactive protein (CRP) concentration was 1.84 ± 6.38 in patients with SFTS (viral disease), whereas 8.49 ± 7.24 in patients with HGA, in which this difference between the 2 groups was significant." (PMID 37100782, 2023). "NEUT were used to distinguish single and mixed infections; PCT, CRP or EO were used to distinguish bacterial and viral infections." (PMID 37822360, 2023). "White blood cells (WBC) and C-reactive protein (CRP) are classical inflammatory markers in bacterial sepsis compared with viral diseases and other inflammatory conditions." (PMID 37143532, 2023). "This is comparable to published data from similar studies, suggesting that CRP is effective for distinguishing both malaria and bacterial infections from viral infections, but cannot separate malaria from bacterial infections in the febrile child on its own." (PMID 37478118, 2023). "Since the viral infection increases C-reactive protein (CRP) and procalcitonin (PCT) values, markers for bacterial infection, a prescription for the bacterial infection is recommended." (PMID 36124445, 2023). "Similar trends were observed when comparing sensitivity and specificity of PCT against CRP in identifying bacterial versus viral infections." (PMID 37760703, 2023). "Examples of protein host response biomarker profiles include FebriDx (not available in the US) or MeMed BV (licensed to Diasorin and Beckman Coulter), which measure MxA/CRP or IP10/TRAIL/CRP, respectively, to discriminate bacterial and viral infections." (PMID 37066874, 2023). "With that in mind, the neonates with other valid reasons for high values of CRP, such as severe birth asphyxia, viral infections and severe brain haemorrhage, were excluded from our study." (PMID 36834338, 2023). "Elevated levels of CRP (alone or in combination with other markers) are indicative of bacterial and viral infections." (PMID 37510958, 2023). "It is worth mentioning that the hs-CRP level is significantly elevated in bacterial infections more than in viral infections." (PMID 35721343, 2022). "CRP is a sensitive indicator of acute systemic inflammatory response after viral infection and tissue injury." (PMID 35685552, 2022). "As a single CRP measurement has limited efficacy in the differential diagnosis between acute bacterial and viral infections, we defined two terms to investigate the early dynamics of CRP over time." (PMID 35897672, 2022). "Accordingly, identification of CRP levels can be an important indirect marker for viral infections and an indicator for progression of infection and effectiveness of the treatment." (PMID 35655792, 2022). "Few studies on CRP kinetics are available to guide intrahospital management of bacterial or viral infections, especially in the ED." (PMID 34983630, 2022). "During an acute febrile illness, the eCRPv value can be used for rapid differentiation between bacterial and viral infection, especially in patients with high CRP values." (PMID 36477474, 2022).